NIPBL (NIPBL cohesin loading factor)
Diseases named in the same sentence as NIPBL in open-access papers (continued):
Sharing a sentence is not in itself a finding about the gene and the disease.
leukemia (1 paper, 2024). A malignant (clonal) hematologic disorder, involving hematopoietic stem cells and characterized by the presence of primitive or atypical myeloid or lymphoid cells in the bone marrow and the blood. "A previous study suggested that the NIPBL protein interacts with KDM6B in leukemia cells." (PMID 38378967, 2024).
neuroblastoma (1 paper, 2025). Neuroblastoma (NB) is the most common solid, extracranial childhood tumor. "We demonstrate that elevated NIPBL expression is associated with undifferentiated, proliferative neuroblastoma cell states and poor clinical outcomes in neuroblastoma patients." (PMID 40867243, 2025). "In this study, we investigate the role of NIPBL in regulating the MYCN–driven transcriptional network in high-risk neuroblastoma." (PMID 40867243, 2025). "Our findings reveal a critical role for NIPBL in shaping the MYCN-driven transcriptional landscape of high-risk neuroblastoma." (PMID 40867243, 2025). "Our study reveals that the cohesin loading factor NIPBL plays a pivotal role in maintaining the MYCN-driven oncogenic transcriptional program in high-risk neuroblastoma." (PMID 40867243, 2025). "To assess the clinical relevance of NIPBL in neuroblastoma, we analyzed the SEQC dataset (GSE49710) of primary neuroblastoma tumors with annotated clinical outcomes to determine whether NIPBL mRNA expression is associated with established clinical and molecular risk factors in neuroblastoma." (PMID 40867243, 2025). "Functional studies revealed that NIPBL is essential for the proliferation of MYCN-amplified neuroblastoma cells, as its depletion significantly reduced cell viability across multiple cell lines." (PMID 40867243, 2025). "Together, these results suggest that NIPBL sustains the undifferentiated state of MYCN-amplified neuroblastoma cells by maintaining MYCN expression and supporting the MYCN-driven repression of neuronal differentiation programs." (PMID 40867243, 2025). "Similar decreases in cell viability were observed in KCNR and IMR-32 cells, indicating that the cohesin loading factor NIPBL is essential for the proliferation of MYCN-amplified neuroblastoma cells." (PMID 40867243, 2025). "Our study demonstrates that NIPBL is aberrantly upregulated in neuroblastoma tumors compared to its normal counterparts, and its elevated expression is associated with unfavorable clinical outcomes." (PMID 40867243, 2025). "To experimentally validate this dependency, we used two independent small interfering RNAs (siRNAs) to deplete NIPBL in MYCN-amplified neuroblastoma cells, BE2C, KCNR, and IMR-32." (PMID 40867243, 2025). "Collectively, we have established a mechanistic link between NIPBL and the MYCN-driven transcriptome, highlighting NIPBL as a potential therapeutic vulnerability to promote differentiation in high-risk neuroblastoma." (PMID 40867243, 2025). "Analysis of patient tumor datasets revealed that NIPBL expression is significantly elevated in neuroblastoma tumors compared to normal adrenal tissue and neural crest-derived precursors." (PMID 40867243, 2025). "While transcription factor–NIPBL cooperation has been proposed as a mechanism for enhancer–promoter specificity in other systems, the role of NIPBL in neuroblastoma, particularly in MYCN-driven oncogenic transcription, remains largely unexplored." (PMID 40867243, 2025). "In summary, our study establishes NIPBL as a central regulator of MYCN-driven transcription in neuroblastoma." (PMID 40867243, 2025). "These transcriptional changes are accompanied by decreased neuroblastoma cell proliferation and increased neuronal differentiation, reflecting impaired regulation of MYCN target genes upon NIPBL loss." (PMID 40867243, 2025). "Mechanistically, NIPBL co-occupies neuroblastoma-specific enhancers with MYCN, particularly at regulatory regions enriched for core regulatory circuitry (CRC) transcription factor binding motifs." (PMID 40867243, 2025). "NIPBL depletion resulted in impaired neuroblastoma cell proliferation, accompanied by global transcriptional reprogramming." (PMID 40867243, 2025). "In contrast, NIPBL peaks that overlapped with MYCN binding were significantly enriched for motifs recognized by core regulatory circuitry (CRC) transcription factors critical to neuroblastoma cell identity, including GATA3, PHOX2A HAND1, and HAND2." (PMID 40867243, 2025).
neuroblastoma (continued). "Interestingly, NIPBL mRNA expression was higher in undifferentiated neural crest cells compared to that of normal adrenal gland tissues and was markedly upregulated in neuroblastoma tumors." (PMID 40867243, 2025). "Given that NIPBL is a critical regulator of enhancer–promoter looping, we sought to determine whether NIPBL expression is dysregulated during neuroblastoma tumorigenesis." (PMID 40867243, 2025). "We sought to determine whether NIPBL plays a direct functional role in the survival and proliferation of neuroblastoma cells." (PMID 40867243, 2025). "Given the growing interest in targeting transcriptional dependencies in MYCN-amplified cancers, therapeutic inhibition of NIPBL will offer a promising strategy to disrupt MYCN-driven oncogenic networks and restore differentiation potential in high-risk neuroblastoma." (PMID 40867243, 2025). "Given that MYCN is a key oncogenic driver in high-risk neuroblastoma and governs a broad transcriptional network, we hypothesized that NIPBL may colocalize with MYCN in the neuroblastoma genome." (PMID 40867243, 2025). "We next tested whether NIPBL depletion induces neuronal differentiation in MYCN-amplified neuroblastoma cells." (PMID 40867243, 2025). "NIPBL mRNA expression was significantly higher in the tumors of neuroblastoma patients compared to normal adrenal gland and neural crest cell samples, suggesting aberrant transcriptional activation during neuroblastoma tumorigenesis." (PMID 40867243, 2025). "Neuroblastoma was identified as one of the top ten tumor types most dependent on NIPBL." (PMID 40867243, 2025). "Together, these results suggest that NIPBL maintains the MYCN-driven transcriptional program that promotes cell proliferation and a stem-like identity in neuroblastoma cells." (PMID 40867243, 2025). "By supporting MYCN expression and enhancer occupancy, NIPBL facilitates the repression of neuronal differentiation programs driven by MYCN, thereby inhibiting the differentiation of neuroblastoma." (PMID 40867243, 2025). "To assess the global transcriptional effects of NIPBL knockdown, we performed RNA-seq analysis on BE2C neuroblastoma cells three days of NIPBL depletion." (PMID 40867243, 2025). "Targeting NIPBL may offer a novel strategy to disrupt MYCN-driven transcription and promote tumor cell differentiation in MYCN-amplified neuroblastoma, ultimately improving therapeutic outcomes in this aggressive pediatric cancer." (PMID 40867243, 2025). "These transcriptional changes were paralleled by the induction of neuronal markers and morphological signs of neuronal differentiation, indicating that NIPBL is essential for maintaining the undifferentiated, stem-like state of MYCN-amplified neuroblastoma cells." (PMID 40867243, 2025). "These NIPBL-bound MYCN peaks are highly enriched for motifs of core regulatory circuitry (CRC) transcription factors such as GATA3, PHOX2A, HAND1, and HAND2, which contribute to the maintenance of the neuroblastoma oncogenic cell identity." (PMID 40867243, 2025). "Our results support a model in which NIPBL promotes MYCN binding at enhancers and sustains its repressive influence on neuronal differentiation programs, thereby reinforcing the MYCN-driven oncogenic transcriptional network that maintains the neuroblastoma phenotype." (PMID 40867243, 2025). "NIPBL mRNA expression was not significantly different between MYCN-amplified and non-amplified neuroblastoma patients." (PMID 40867243, 2025).
nevus (1 paper, 2021). Nevus (or naevus, plural nevi or naevi, from nævus, Latin for "birthmark") is the medical term for sharply circumscribed[1] and chronic lesions of the skin or mucosa. "NIPBL, AKAP9, and EP400 were mutated in both the nevus and atypical tumor, although the specific mutations were different between the two lesions." (PMID 35052351, 2021).
oligodendroglioma (1 paper, 2017). A well-differentiated (WHO grade II), diffusely infiltrating neuroglial tumor, typically located in the cerebral hemispheres. "NIPBL is a regulatory subunit of the cohesin complex that plays a central role in chromatin structure that has been implicated in other cancers but not oligodendroglioma." (PMID 28388591, 2017).
prostate carcinoma (1 paper, 2019). A carcinoma that arises from epithelial cells of the prostate gland. "While the biological function of the NIPBL-ERG fusion at present is not known, given the lack of mechanistic studies, our findings suggest that the fusion exerts its function in an analogous manner to TMPRSS2-ERG in prostate cancer." (PMID 31906059, 2019).
cancer (23 papers, 2015 to 2026). A tumor composed of atypical neoplastic, often pleomorphic cells that invade other tissues. "In contrast, the NIPBL missense mutation (p.Val469Leu) was restricted to epithelial-derived malignant carcinomas, potentially reflecting involvement in chromosomal cohesion defects characteristic of glandular malignancies." (PMID 41168812, 2025). "From the clinical perspective, NIPBL and cohesin subunits are frequently mutated in fast-growing cancers such as AML." (PMID 35353576, 2022). "Moreover, higher expression of NIPBL in cancer tissues was strongly associated with poorer prognosis of NSCLC patients." (PMID 38378967, 2024). "NIPBL gene mutations are also associated with malignant neoplasms." (PMID 36686800, 2022). "We also checked whether cancers with truncating mutations in the N-terminus of NIPBL are associated with a significantly lower CNA number as compared to those with truncating mutations in the C-terminus." (PMID 27831464, 2016). "While the functional elements occupied by Mediator, Cohesin and NIPBL are similar in the three cancer cells investigated, the coordinates of these elements are different." (PMID 27739523, 2016). "Transcription factors were ranked based on their percentage of overlap with MED1, SMC1A and NIPBL across the genome of each cancer cell." (PMID 27739523, 2016). "Taken together, these results suggest a conserved function of Mediator, Cohesin and NIPBL in the control of regulatory elements throughout the genome of cancer cells." (PMID 27739523, 2016). "We therefore tested whether mutations in the HEAT domain, which is necessary to target NIPBL to sites of DNA damage, have a stronger effect on CNA number in cancers than do other missense mutations." (PMID 27831464, 2016). "Given that the STAT3-related pathway is constitutively activated in diverse cancers, and acts as a potent pro-survival and anti-apoptotic signaling protein, these data demonstrated that NIPBL silencing inhibited cell growth, possibly via downregulating STAT3 and STAT3 target genes in NSCLC cells." (PMID 25963978, 2015). "To further test the functional significance of our cancer therapy results that NIPBL expression affected sensitivity to chemotherapeutic drug responses, we investigated the effect of downregulating endogenous NIPBL expression on cell growth after exposure to chemotherapeutic drugs." (PMID 25963978, 2015). "In support of this model, elevated expression of almost every cohesin subunit (RAD21, SMC1A, SMC3, STAG1, PDS5, WAPL) and cohesin regulator (NIPBL, MAU2) appears to be oncogenic and present in a wide range of cancer cells." (PMID 41370327, 2025). "To define the contribution of Mediator and Cohesin to the regulation of the cancer transcriptional program, we established the genome-wide occupancy of MED1 (Mediator), SMC1A (Cohesin) and the cohesin loader NIPBL." (PMID 27739523, 2016). "Others, such as TCF12 and NIPBL, are less commonly associated with cancer or drug resistance; TCF12 is classified as a lower-confidence cancer gene in OncoKB, and NIPBL is not listed, suggesting potential novel roles in mediating transcriptional reprogramming." (PMID 41492468, 2026). "In light of this NIPBL-BET interplay, it might be of interest to investigate the sensitivity to BET inhibitors in cancer cells with cohesin defects, to check for a higher susceptibility, allowing the use of lower doses of BET inhibitors." (PMID 34386522, 2021). "However, the mechanistic effect of RAD21 or NIPBL in cancers, including NSCLC, is largely unclear, and further studies are needed to determine whether RAD21 or NIPBL could be an indicator for the use of PI3K inhibitors in NSCLC." (PMID 38378967, 2024).
cancer (continued). "No NIPBL fusions have been reported in human cancers thus far." (PMID 31906059, 2019). "Whether or not cancer cells are dependent on Mediator, Cohesin and NIPBL to maintain their proliferative state is not known." (PMID 27739523, 2016). "Although these results and analyses implied that abnormal NIPBL may be a significant feature or might contribute to carcinogenesis, there are no data currently available from clinical cancer samples." (PMID 25963978, 2015). "Anchored multiplex PCR (AMP) for next-generation sequencing utilizing a customized panel targeting 86 cancer-related genes was performed, and it identified novel non-CSF1-driven gene fusions: NIPBL-ERG, FN1-ROS1, and YAP1-MAML2." (PMID 31906059, 2019).
tumor (11 papers, 2015 to 2025). "We found that elevated NIPBL expression is associated with poorly differentiated tumor phenotypes and worse clinical outcomes." (PMID 40867243, 2025). "In recent years, dysregulation of NIPBL has been associated with tumor insurgence, in particular, in hematological malignancies." (PMID 33352756, 2020). "To confirm the functional significance of our clinicopathological results that NIPBL expression was associated with tumor metastasis, we determined the effect of NIPBL downregulation on cell migration and invasion in H1299 and H1650 cells." (PMID 25963978, 2015). "Moreover, high expression of NIPBL was associated lymph node metastasis and tumor differentiation." (PMID 30713220, 2019). "Elevated NIPBL expression correlates with poor clinical outcomes and an undifferentiated tumor phenotype." (PMID 40867243, 2025). "Case 1 harbored a NIPBL (NM_015384.4: exon: 1)/ERG (NM_004449.4: exon: 1) in-frame fusion in the tumor cells arising from a translocation involving loci 5p13.2 and 21q22.2, respectively." (PMID 31906059, 2019). "We found that NIPBL expression was positively correlated with tumor differentiation (P = 0.003) and lymph node metastasis (P = 0.029)." (PMID 25963978, 2015). "Filtering yielded 46 likely somatic mutations in the tumor, of which 7 (affecting EIF4A1, EPHA3, FAF1, IPO8, KIAA1377, LIMCH1, and NIPBL) were confirmed in the RNASeq results." (PMID 25861239, 2015). "Immunohistochemical analysis showed that high expression of NIPBL was strongly correlated with poor prognosis, tumor differentiation, and lymph node metastasis." (PMID 25963978, 2015). "NIPBL was also reported to be important for tumor development." (PMID 30713220, 2019). "Moreover, the NIPBL-ERG fusion in Case 1 was identified in both recurrences at 7 and 14 months, implying a common pathogenic theme for local recurrence in this specific tumor." (PMID 31906059, 2019). "Other novel tumor suppressor genes identified here include KANSL1, a scaffold protein for histone acetylation complexes, BMPR2, a receptor serine/threonine kinase for bone morphogenetic proteins, MAP2K7, involved in MAP-kinase signaling, and NIPBL, a member of the cohesin complex." (PMID 29056346, 2017).
) malformation syndrome (2 papers, 2018 to 2022). "CdLS, an autosomal dominant (NIPBL, SMC3, and RAD21) or X-linked (SMC1 and HDAC8) malformation syndrome, represents the best characterized cohesinopathy." (PMID 36467423, 2022). "The best characterized cohesinopathy is CdLS, an autosomal dominant (NIPBL, SMC3, and RAD21) or X-linked (SMC1A and HDAC8) malformation syndrome." (PMID 36467423, 2022).
haematological diseases (2 papers, 2020). "Thus, also in the absence of RUNX1 translocation or mutations, additional factors such as defects in the expression of NIPBL might induce haematological diseases." (PMID 32323916, 2020). "Thus, also in the absence of RUNX1 translocation or mutations, additional factors such as defects in the expression of NIPBL observed in AML patients might contribute to haematological diseases." (PMID 32323916, 2020).
neurodevelopmental disorder (1 paper, 2025). A behavioral and cognitive disorder with onset during the developmental period that involves impaired or aberrant development of intellectual, motor, or social functions. "Group 1—Severe multisystem neurodevelopmental disorders (Transcriptional/RNA-processing phenotype): This group included patients carrying variants in POLR1C, TCF4, HNRNPU, NIPBL, and ACTG1." (PMID 41300846, 2025).
NIPBL also shares sentences with these, for which no sentence is quoted: genetic disorder (5 papers); chronic atrial and intestinal dysrhythmia (4); infection (3); Warsaw breakage syndrome (3); colon cancer (2); congenital heart disease (2); COVID-19 (2); Kabuki syndrome (2); Noonan syndrome (2); Alagille syndrome (1); Alpha-thalassemia (1); atrial septal defect (1); autosomal recessive primary microcephaly (1); Baraitser-Winter syndrome (1); breast adenocarcinoma (1); CHOPS syndrome (1); Cognitive impairment (1); colorectal tumors (1); congenital myopathies (1); cryptorchidism (1); developmental disabilities (1); diaphragmatic hernia (1); embryonic carcinoma (1); endolymphatic hydrops (1); Ewing sarcoma (1); glaucoma (1); heart diseases (1); Hodgkins lymphoma (1); intrahepatic cholangiocarcinoma (1); melanoma (1).
A further 17 diseases each share a sentence with NIPBL in 1 paper.